ERBB2 (erb-b2 receptor tyrosine kinase 2)
Diseases named in the same sentence as ERBB2 in open-access papers (continued):
Sharing a sentence is not in itself a finding about the gene and the disease.
tumor (continued). "MET, ERBB2, VEGFR2, PFGFR, and EGFR, among others, represent acknowledged targets of semaphorins often associated with tumor progression or poor prognosis." (PMID 38067240, 2023). "The addition of ERBB2/4 inhibitors in combination would also be worthy of study, given their role in invasion and tumour progression." (PMID 36357571, 2023). "In summary, herein, we demonstrate the feasibility of using ctDNA and circulating tumor cells (CTCs) for both ERBB2/HER2 assessment and its kinetics to determine early response to a targeted therapy regimen." (PMID 40028484, 2023). "For example, development of anti-HER2 agents has been clinically successful in treatment of ERBB2-amplified tumours." (PMID 36804485, 2023). "Ablation of each ERBB family member, especially the loss of EGFR or ERBB2/HER2, altered signaling downstream of the other three ERBB receptors and decreased cell proliferation, migration, and tumor growth." (PMID 37341059, 2023). "Candidate tumor-agnostic molecular targets in the three gynecological malignancies included ERBB2, PIK3CA, ARID1A, and KRAS." (PMID 38201563, 2023). "β4 integrin enhances the erythroblastic oncogene B2 (ErbB2)‐dependent vascular endothelial growth factor (VEGF) expression by tumour cells, promoting their adhesion to microvascular endothelium." (PMID 37830128, 2023). "Several nuclear hormone receptors showed changed expression in tumours with high levels of ERBB2 with some being elevated (ESRRA) whereas others were either unchanged (HNF4A) or showed reduced levels (PPARA)." (PMID 36153371, 2022). "ErbB2 protein is overexpressed in many cancers and have been exploited as a convenient tumour marker and target in many anti-cancer immunotherapies and the number of anti ErbB2/Her2 therapies continues to grow." (PMID 36498915, 2022). "Conversely, HER2 sensitivity of tumours that meet only one criterion is similar to non-HER2-E/ERBB2-low disease." (PMID 35158778, 2022). "Equivocal cases are defined by moderate (2+) expression in ≥50% or 3+ ERBB2 in more than 10% but less than 50% of tumor cells." (PMID 35954382, 2022). "Somatic ERBB2 mutations occur in approximately 3% of TNBC, and a subset of TNBC tumours are classified as HER2-enriched by gene expression." (PMID 36003779, 2022). "Studies in cell line and xenograft models have indicated that increased ErbB2 signaling can contribute to the restoration of AR activity and tumor growth in CRPC." (PMID 35645241, 2022). "Among all analogs, BIIB021 represented one of the HSP90 inhibitors with the most efficacious activity and showed a high selectivity for tumor versus normal cells in the ERBB2 degradation assays with a pyridylmethylene group at the 9-position." (PMID 36139353, 2022). "The median (range) age was similar in both groups (61.0 [22.0-103.0] years for the ERBB2-low group vs 61.0 [22.0-96.0] years for the ERBB2-zero group) as well as menopausal status, tumor grade, and number of metastatic sites." (PMID 36107428, 2022). "Amplification in ERBB2 in these neoplasms represents a novel finding and a potential target for precision oncology." (PMID 36056133, 2022). "Gefitinib, crizotinib and afatinib are kinase inhibitors that are used to treat tumours that exhibit EGFR mutations, ALK fusions and ERBB2/HER2-amplification, respectively." (PMID 35781872, 2022). "First, to mimic the very low quantity of tumor DNA in plasma, the tumor FFPE-DNA of a HER2 3+ patient (ERBB2 CNV = 100) was serially diluted with water and then analyzed by ddPCR." (PMID 35565309, 2022). "Similar to EGFRvIII, human epidermal growth factor receptor 2 (HER2/ErbB2) has been proposed as a potential candidate for a tumor antigen." (PMID 36305981, 2022). "Analysis of tumor immune infiltration showed that the expressions of AR and ERBB2 were correlated with the abundance of immune infiltration and made a difference in clinical outcomes." (PMID 35069767, 2022).
tumor (continued). "The data of qRT-PCR showed that IPO7 and ERBB2 expression were remarkably down-modulated in the tumor tissues of IPO7 knockdown group." (PMID 35588577, 2022). "The IHC staining of ERBB2 showed the higher protein expression levels in tumor tissues than normal tissues in SBA." (PMID 36104333, 2022). "Human epidermal growth factor receptor 2 (HER-2, also known as HER-2 neu or ErbB-2) is also a noteworthy tumor marker." (PMID 36288138, 2022). "For instance, ERBB2, the receptor of HER2, differentially expressed in multiple tumor areas on the same ST slide." (PMID 36313703, 2022). "Based on protein abundance ratio (CPTAC dataset), the BiP-L group was significantly correlated with ER, PR, and ERBB2 positivity and with a higher estimate tumor purity score." (PMID 36547124, 2022). "In BC, the current molecular classification divides the tumor into five groups, namely luminal A, luminal B, ErbB2/Her2+, basal and normal-like." (PMID 36287050, 2022). "PPI analysis revealed 22 genes for MECa and 63 for AdCC that were validated by Kaplan–Meier that showed FN1 and SPP1 for MECa, and EGF and ERBB2 for AdCC as more significant candidate genes for each neoplasm." (PMID 36146635, 2022). "As reported, Par3 shows the function of higher-grade tumor inhibition with the activation of the ErbB2 or Ras pathway." (PMID 35875120, 2022). "In the ERBB2-low group, tumor grades were mainly II and III (89.6%), similar to the ERBB2-zero group." (PMID 36107428, 2022). "The inferred tumor ERBB2 ploidy was generally stable in both of the two patients, so ERBB2 ploidy change in cfDNA was influenced by tumor fraction." (PMID 35379811, 2022). "Several strategies have been developed to target the key role of ERBB2 signaling in tumor development and progression." (PMID 35497981, 2022). "ERBB2 heterogeneity is one of the factors affecting diagnosis; it is characterized by differential expression or amplification within the same tumor (intratumoral) or in cancers from various sites or time points in the same patient (intertumoral)." (PMID 36291943, 2022). "It is possible that the abnormal profiled abundance of differential bacteria causes changes in the expression of PTEN, ERBB2, ERBB4, and MET and stimulates tumor growth." (PMID 35739509, 2022). "Given the crucial role of HER2 in individualised tumour intervention, we first characterised ERBB2 in multiple human cancers in a multifaceted manner." (PMID 35990657, 2022). "The samples of each tumour type were classified into two groups based on ERBB2 expression, with the top 30% and lowest 30% comprising the pathways related to ERBB2." (PMID 35990657, 2022). "Both ERBB2 and ERBB2d16 were detectable in each specimen, the ERBB2d16 isoform was present at a relatively high level in about half of the tumor samples examined (53/110)." (PMID 35463314, 2022). "In a pan-cancer analysis, 67% of primary tumors have a high ERBB2 gene copy number, and 31% of primary tumors present a low level of ERBB2 compared with their non-tumor tissues in the TCGA database." (PMID 36172165, 2022). "A retrospective mRNA-based analysis for ERBB2, using qRT-PCR for baseline tumour samples from the chemotherapy-free arm, showed 23.4% and 10.9% pCR rates in ERBB2-high and ERBB2-low groups, respectively." (PMID 35158778, 2022). "The highly expressed ERBB2 was deemed to participate in cancer progression, promoting tumor proliferation, invasion, and metastasis." (PMID 36437939, 2022). "In some carcinomas, glycoproteins such as the EGFR and ErbB2 function as critical oncogenes that consistently drive the tumor phenotype." (PMID 35371997, 2022). "Higher SETD7 mRNA and protein in Her2-enriched tumours was correlated with increased ERBB2 amplification and corresponding ERBB2 mRNA upregulation." (PMID 36551516, 2022).
tumor (continued). "Peptides used to develop vaccines are derived from tumor-associated antigens or tumor-specific antigens, such as HER-2, MUC1, ErbB2, CEA, FRα, MAGE A1, A3, and A10, NY-ESO-1, among others." (PMID 36016136, 2022). "The dimerization of EGFR and ErbB2 (HER2) is associated with a poor prognosis and with cell invasion in a range of tumours." (PMID 35781872, 2022). "Tumours harbouring mutations in genes such as EGFR and ERBB2, or gene rearrangements involving ALK, RET, or ROS1 are typically dependent on the oncogene for survival, with profound anti-tumour effects observed in response to the appropriate targeted therapy." (PMID 35326531, 2022). "The majority of the 39 monogenic rare variant containing genes are either well-known tumor suppressors or suspected to have a tumor suppressor role, whereas only PPM1D and ERBB2 are classified as bonafide oncogenes by the Cancer Gene Census." (PMID 34755241, 2022). "To date, immunohistochemistry and in situ hybridization are the gold standard methods for assessing HER2/ERBB2 overexpression/amplification in tumor specimens." (PMID 35565309, 2022). "ER-negative tumor amplifications were also focused on ERBB2 with less frequent amplifications of AKT1, CDKN1B, FOXO3, GATA3, KRAS, PIK3CA and TBL1XR1." (PMID 36140723, 2022). "The overexpression (intense membrane staining of >10% of tumour cells by immunohistochemistry) and/or amplification of the ERBB2 gene locus, which codes for HER2, is necessary for classification as HER2+ tumours." (PMID 35242228, 2022). "Four estimation algorithms revealed that the more ERBB2 gene enriched in the tumor cluster of KICH and KIRC patients, and less cancer-associated fibroblast infiltrated in the immune cell cluster of KICH and KIRC patients." (PMID 36172165, 2022). "For example, we found that ERBB2 is enriched in the tumor region detected by SpatialPCA while TRAF2 is enriched in the tumor surrounding region detected by SpatialPCA." (PMID 36418351, 2022). "Traditionally, tumor grade, tumor size, lymph node status, estrogen (ER), progesterone (PgR), and human epidermal growth factor (HER2/neu or c-erbB2) receptor status have represented the main prognostic markers for BC." (PMID 36428728, 2022). "In the present research, we analyzed the distribution of the ERBB2 gene in various types of tumor populations and comprehensively explored the connections between ERBB2 copy number and clinicopathological characteristics." (PMID 36172165, 2022). "One example is a fatal case to treat ERBB2 overexpressing tumour with HER2‐targeting CAR‐T cells which triggered severe toxicities in the patients’ lungs." (PMID 36495108, 2022). "ERBB2 status is also related to tumor sidedness; the rectum and left colon are frequently the sites of early-stage malignancies with ERBB2 amplification, which most likely results from variables affecting germinal developmental differences." (PMID 36291943, 2022). "In tumor progression, ERBB2 interacts with epidermal growth factor receptors (EGFRs) and activates signaling pathways of tumor proliferation." (PMID 35069767, 2022). "Post hoc analyses of pretreatment tumor specimens via targeted sequencing indicated that ERBB2 amplification, RTK/RAS pathway alterations, and high neoantigen load corrected by HLA-B were positively related to survival." (PMID 36224176, 2022). "It is found that the high expression of ERBB3 in tumor tissues is consistent with the high expression of ERBB2." (PMID 35581263, 2022). "A genetic analysis using the Oncomine Dx Target Test Multi-CDx System revealed that the primary tumor was positive for ERBB2." (PMID 36411591, 2022). "Amplification of ERBB2 was observed in tumour from another patient (patient 45), captured through regions of altered copy number in plasma, at a lower amplitude consistent with the low fractional abundance of ctDNA amongst non-tumour cfDNA." (PMID 35392854, 2022).
tumor (continued). "ERBB2 gene demethylation leads to a poor prognosis in cancer patients, which is strongly influenced by the composition and abundance of tumor immune cell infiltration." (PMID 36172165, 2022). "When HIFU is combined with anti-PD-1, tumor proliferation-related genes such as Wnt7b,S100a14 and Erbb2 are significantly downregulated, and newly released tumor-specific antigens, cytokines, and cell fragments act as agonists of innate immunity." (PMID 36032103, 2022). "The HER2-enriched tumours are one of the subtypes defined by the PAM50 BC tumour subtyping and are characterised with the highest ERBB2 gene expression amongst all subtypes both at RNA and protein level." (PMID 35158855, 2022). "High concordance of HER2 amplification between baseline ctDNA and tumour tissue has been demonstrated, and the co-presence of baseline PIK3CA/R1/C3 or ERBB2/4 mutations in ctDNA were associated with poor PFS." (PMID 35954487, 2022). "In another study, comprehensive circulating tumor deoxyribonucleic acid (ctDNA) NGS successfully detected ERBB2 amplification in 96.6% (28/29) of the intent-to-treat group; this indicates that ctDNA can serve as a substitute for tissue." (PMID 36291943, 2022). "At the same time, it is important to highlight those 30.0% of patients in PerELISA who had HER2DX ERBB2 mRNA-low tumours." (PMID 36374768, 2022). "ErbB2 CAR-T cells pose a risk of lethal toxicity, including cytokine release syndrome resulting from the “on-target, off-tumor” recognition of ErbB2." (PMID 36140319, 2022). "As expected, we observed high prediction accuracy for ERBB2 gains but only when tumor cell phenotypes were used as predictors (AUC 0.76)." (PMID 35437329, 2022). "Here we report on the relation between genetic alterations and tumor cell proliferation following pET, with a special reference to ILC and ERBB2 mutation." (PMID 35842479, 2022). "ERBB2 gain-of-function procures immune cell infiltration for tumor growth and drives away T regulatory cells, which suppress or downregulate induction and proliferation of effector T cells." (PMID 36172165, 2022). "We, in collaboration with cResponseTM, have shown that prior chemotherapy administration in OC patients leads to the down-regulation of ErbB2 expression in the tumor." (PMID 36140319, 2022). "GW-2974 is a highly potent tyrosine kinase receptor that inhibits EGFR and ERBB-2 in tumor cells with selectivity for tumor cells over normal cells." (PMID 36476719, 2022). "Activation of ERBB2 signaling enhances tumor growth and can act synergistically with KRAS to promote the aggressiveness of PC cells." (PMID 35588577, 2022). "The Erbb2 inhibitor lapatinib, when combined with lovastatin, significantly decreased tumor volume and weight compared to control-treated and lapatinib-treated HER2-positive xenografted mice." (PMID 36579200, 2022). "High ERBB2 copy number variation (CNV) in cfDNA was associated with a shorter survival, and an increase in ERBB2 CNV was detected at the time of tumor progression." (PMID 35565309, 2022). "On the 21st day after transplantation, the tumor growth of cells expressing ERBB2 E401G was found to be significantly increased compared to that of cells expressing ERBB2 WT." (PMID 34997908, 2022). "High expression of ERBB2 not only regulates malignant biological behavior but also enhances tumor radio-resistance, leading to metastasis and poorer treatment response." (PMID 37304410, 2022). "A summary of ERBB2 fusion tumor patients’ demographic and clinical characteristics in Chinese cohort." (PMID 36276102, 2022). "Even so, a proportion of ERBB2-mutant ILCs still showed optimal suppression of tumor cell proliferation by pET." (PMID 35842479, 2022). "One limitation of the study is our inability to determine the prevalence of ERBB2 alterations by tumor type as some tumors where NGS testing has been commonplace for longer, such as NSCLC, are likely to be over-represented in our database." (PMID 35126865, 2022).
tumor (continued). "Further, the reduced expression level of PTPRO is associated with tumor size, poor histological differentiation, increased tumor depth, ERBB2, and Ki67 expression as well as shorter patient survival." (PMID 35431974, 2022). "Previous studies have indicated a role for Brk in tumour development alongside ErbB2 overexpression in an immortalized, mouse mammary cell line that retains normal morphology and function in vitro." (PMID 35327957, 2022). "Using solid biopsies to identify ERBB2 amplifications indicative of HER2 positive tumours and employing targeted HER2 therapies is nowadays well established in the clinics." (PMID 35158855, 2022). "All patients had a diagnosis of ERBB2+ (IHC II+ or III+ or FISH+) metastatic breast cancer and the ERBB2 status was confirmed from a biopsy obtained from tumor tissue." (PMID 35379811, 2022). "In the samples included in this study ERBB2 (HER2) status was previously established on tumor tissue by immunohistochemistry (IHC) as well as by FISH and on CTCs from matched blood samples collected from the same patients." (PMID 35714131, 2022). "Conceivably, the ability of ErbB2 to downregulate BLNK depends on the degree of ErbB2 upregulation in the tumor." (PMID 35933456, 2022). "Tumours that have a high expression signature of the main drug target and excessive activation of the HER2 and/or EGFR pathway (i.e., ERBB2-high and HER2-E) are potentially most sensitive to anti-HER2-targeted therapies." (PMID 35158778, 2022). "Activating mutations were identified in tumor samples including EGFR L858R, EGFR T790M, EGFR exon 19 deletion, ERBB2 amplification, ALK fusion, KRAS G12C." (PMID 35123506, 2022). "The human epidermal growth factor receptor 2 (HER2/Neu/ErbB2) is amplified and/or overexpressed in approximately 15% of human breast cancers and plays a direct role in tumor development." (PMID 35138529, 2022). "A summary of ERBB2-KD fusion tumor patients’ demographic and clinical characteristics in Chinese cohort." (PMID 36276102, 2022). "The client proteins of Hsp90 include Her2/ErbB2, v-Src, Hif-1a, Raf-1, Akt, hTERT, etc., which are involved in tumor survival and growth, and whose expressions are upregulated in cancer cells." (PMID 35455409, 2022). "For example, ERBB2 expression in CRC cells is often restricted to the basolateral membranes of tumor cells and stains uniformly across the tumor." (PMID 35954382, 2022). "The NGS GeneRead analysis of tumor tissue cells showed the consistent mutations of KRAS and ERBB2 as carried by urinary exosomes from the same BC patient." (PMID 35787656, 2022). "This included focal amplification of ERBB2 (chromosome 17) in tumour from patient 45, identified as amplifications (P1-P4) and gains in copy number (P5) across matched serial plasma." (PMID 35392854, 2022). "Further immunohistochemistry assays showed that FTO knockdown inhibited the expression of Vimentin and E-cadherin, indicating an inhibiting effect of tumor metastasis, whereas ERBB2 has a reverse effect." (PMID 35524932, 2022). "UroAmplitude identified TERT, PLEKHS1, FOXQ1, KMT2C, and ERBB2 somatic events in urine collected prior to resection of an HG T1 multifocal tumor." (PMID 36233691, 2022). "To examine tumor forming capacity in vivo, we constructed H460 cells that stably express ERBB2 and assessed tumor growth after subcutaneous inoculation of these cells into mice." (PMID 34997908, 2022). "As the repeated tumor biopsy still revealed ERBB2 expression, trastuzumab emsantine (T-DM1) 3.6 mg/kg q3w was administered for three cycles but unfortunately without success." (PMID 34367146, 2021).